IL4R (interleukin 4 receptor)
Diseases named in the same sentence as IL4R in open-access papers (continued):
Sharing a sentence is not in itself a finding about the gene and the disease.
Pruritus (10 papers, 2021 to 2025). Pruritus is an itch or a sensation that makes a person want to scratch. "Across disorders, pathway-directed biologics against IL-4Rα, IL-13, and IL-31R consistently reduce disease activity and pruritus in AD and prurigo nodularis, with emerging signals of benefit in bullous pemphigoid and chronic spontaneous urticaria." (PMID 41226755, 2025). "Th-2 profile cytokines, such as IL-4, IL-5 and IL-13, play a significant role in the pathogenesis of the disease by switching the immunoglobulin class to IgE and stimulating afferent neurons via IL-4Rα, thereby promoting pruritus." (PMID 34948183, 2021). "Previous studies have indicated that IL-31, IL-4Rα, JAK1, and HRH4 are strongly associated with pruritus in AD." (PMID 34970141, 2021). "In addition, IL-4 and IL-13 together induce the conversion of immunoglobulins to IgE in B cells and stimulation of afferent neurons via the IL-4 receptor subunit-α (IL-4Rα) to promote pruritus." (PMID 39697554, 2024). "Treatment of AD patients with an anti-human IL-4Rα antibody (dupilumab) that inhibits binding of IL-4 and IL-13 to IL-4Rα improved the signs and symptoms of AD (including pruritus), anxiety and depression, as well as the quality of life, compared to placebo controls." (PMID 35874756, 2022). "Similarly, a positive correlation with pruritus NRS was observed for IL4R, CXCR1, TGFB1, IL13RA2." (PMID 41268562, 2025). "Perhaps the effectiveness of dupilumab in treating PN may be explained by disruption of the itch-scratch cycle via inhibition of neuronal IL-4Rα, which is required for transduction of chronic itch signaling, and results in attenuation of pruritus and skin inflammation." (PMID 36966024, 2023).
schistosomiasis (10 papers, 2008 to 2019). An infectious disease caused by parasitic trematodes of the genus Schistosoma that colonize human blood vessels and release eggs that can cause granulomatous reactions leading to acute (swimmer's itch or acute schistosomiasis syndrome) or chronic disease. "In the high dose model, we found that mice deficient in IL-4Rα-expressing B cells were more susceptible to acute schistosomiasis than B cell-deficient (μMT) mice, succumbing to infection at the acute stage whereas μMT mice survived until the chronic stage." (PMID 30619289, 2018). "In summary, we have demonstrated that selective deletion of IL-4Rα on B cells renders mice more susceptible to acute schistosomiasis than B-cell deficient mice." (PMID 30619289, 2018). "We found that mice carrying a specific deletion of IL-4Rα on B cells succumbed quickly to schistosomiasis compared to littermate control and B cell-deficient mice." (PMID 30619289, 2018). "To address this, we examined B cell-specific IL-4Rα-deficient (mb1creIL-4Rα−/lox) mice in three experimental models of schistosomiasis: high-dose (100 cercariae), low dose (30 cercariae), and a synchronous egg challenge." (PMID 30619289, 2018). "More recently, using Schistosomiasis-infected IL-4Rα deficient mice, we and others demonstrated reduced fibrogranulomatous inflammation." (PMID 28827803, 2017). "Using inducible IL-4Rα deficient mice in the present study, we now dissected the role of IL-4/IL-13-mediated type 2 responses during acute and chronic murine schistosomiasis." (PMID 28827803, 2017). "Interleukin-4 receptor (IL-4Rα) is critical for the initiation of type-2 immune responses and implicated in the pathogenesis of experimental schistosomiasis." (PMID 28827803, 2017). "Amelioration of chronic schistosomiasis pathology was further associated with reduction of type 2 immune effector responses but expansion of regulatory T and B cells, suggesting that IL-4Rα mediated immune responses are detrimental in chronic schistosomiasis." (PMID 28827803, 2017). "Previous studies with IL-4Rα−/− and some IL-4-deficient mice demonstrated that development of the Th2 response is critical for survival in schistosomiasis, especially during the early stages of infection." (PMID 18369473, 2008). "Interrupting IL-4Rα mediated signaling during the acute phase impaired the development of protective type-2 immune responses, leading to rapid weight loss and premature death, confirming a protective role of IL-4Rα during acute schistosomiasis." (PMID 28827803, 2017). "Taking advantage of a newly established temporal inducible IL-4Rα deficient mouse model, we demonstrated that interrupting IL-4Rα mediated signaling prevents the onset and maintenance of egg-driven type 2 immune responses and its associated fibro-granulomatous inflammation during schistosomiasis." (PMID 28827803, 2017). "Hence, the immune and histopathological response of Tam2-fed RosaCreERT2-/+IL-4Rα-/lox mice (termed iCre-/+IL-4Rα-/lox Tam2), which might associate with the host premature death during experimental schistosomiasis was dissected." (PMID 28827803, 2017). "Moreover, congenital IL-4Rα deletion has now been shown to affect the development of animals, challenging our current knowledge on the role of IL-4Rα throughout experimental schistosomiasis (acute and chronic) using mouse models of constitutive IL-4Rα deficiency." (PMID 28827803, 2017). "Together, these data demonstrate that IL‐4Rα‐expressing CD11c+ cells play an important role in maintaining cellular immunity during schistosomiasis in mice." (PMID 30500088, 2019). "Development of IL‐4 receptor alpha (IL‐4Rα)‐dependent cellular immunity regulates host protection against acute schistosomiasis." (PMID 30500088, 2019). "Together, these data demonstrate that IL‐4Rα signaling on CD11c+ cells is important for driving cellular immunity during acute schistosomiasis." (PMID 30500088, 2019).
schistosomiasis (continued). "In this study, we investigated the immunomodulatory role of IL-4Rα expressing B cells during schistosomiasis." (PMID 30619289, 2018). "First, in an experimental murine model of schistosomiasis, we demonstrated that Foxp3+ Treg cells up-regulated IL-4Rα expression." (PMID 30379806, 2018). "In this study, we examined the role of IL-4Rα expressing B cells in driving immunoregulation of inflammatory granulomatous tissue pathology during schistosomiasis." (PMID 30619289, 2018). "Taken together, our findings indicate that within the B cell compartment, IL-4Rα-expressing B cells in particular down-modulate the deleterious egg-driven tissue granulomatous inflammation to enable host survival during schistosomiasis in mice." (PMID 30619289, 2018). "Further analyses on the need for the host to up-regulate this receptor during schistosomiasis were then conducted using a murine model of specific deletion of IL-4Rα within the Foxp3+ Treg cell population, termed Foxp3cre IL-4Rα−/lox mice." (PMID 30379806, 2018). "Our findings further confirmed a protective role played by IL-4Rα mediated signaling during acute schistosomiasis." (PMID 28827803, 2017). "Using reverse genetics, loss-of-function mouse models have helped uncover a protective role for Interleukin-4 receptor (IL-4Rα) in the host survival to experimental schistosomiasis." (PMID 28827803, 2017). "Conversely, IL-4Rα removal at the chronic phase of schistosomiasis ameliorated the pathological fibro-granulomatous pathology and reversed liver scarification without affecting the host fitness." (PMID 28827803, 2017). "In summary, we provide evidence on the role of IL-4Rα during experimental schistosomiasis whereby early signaling helps the host survive the acute phase of the disease whereas signaling at the late chronic phase mediate the morbidity." (PMID 28827803, 2017). "IL-4Rα mediated type-2 responses are critical for the control of pathology during acute schistosomiasis." (PMID 28827803, 2017). "Taken together our results suggest that IL-4Rα mediated signaling differentially regulates schistosomiasis disease depending on the stage of the infection." (PMID 28827803, 2017). "This further re-emphasizes the potential of IL-4Rα in modulating the dynamics of the host regulatory responses during chronic diseases such as schistosomiasis." (PMID 28827803, 2017). "Together, these results demonstrate that knocking down IL-4Rα at the early acute phase of experimental schistosomiasis considerably diminishes host ability to subsequently mount a type-2 immune response." (PMID 28827803, 2017). "Most notably, Arg1 mRNA was not reduced, yet Arg1 expression in macrophages is predominantly driven by an IL-4Rα/STAT6-dependent mechanism in schistosomiasis." (PMID 25211233, 2014). "These unexpected results led us to reexamine the role of IL-4Rα-expressing AAMs in the pathogenesis of schistosomiasis." (PMID 25211233, 2014). "IL-4Rα-dependent responses are essential for granuloma formation and host survival during acute schistosomiasis." (PMID 20502521, 2010). "Because production of the soluble IL-13Rα2 is IL-4Rα-, IL-13Rα1-, and Stat6-dependent, these data combined with the schistosomiasis studies suggested that the Retnla−/− mice were developing stronger IL-4/IL-13 responses following infection." (PMID 19381262, 2009). "To investigate whether IL-4Rα expressing B cells contribute to the B-cell mediated host resistance to schistosomiasis, we infected mb1creIL-4Rα−/lox, μMT and IL-4Rα−/lox mice with 100 live S. mansoni cercariae and monitored them over a 13 weeks period." (PMID 30619289, 2018). "We also investigated whether IL-4Rα expressing B cells were required to downregulate gut pathology during the chronic stages of schistosomiasis." (PMID 30619289, 2018).
schistosomiasis (continued). "Taken together, these data suggest that the specific deficiency of IL-4Rα expressing B cells is equally if not more deleterious to the host than the general lack of B cells during acute schistosomiasis." (PMID 30619289, 2018). "We have found that IL-4Rα signaling on macrophages and neutrophils, smooth muscle cells, and pan-T cells individually contribute to driving host protective immunity and down-modulating excessive tissue pathology during acute schistosomiasis." (PMID 30619289, 2018). "A protective role for IL-4Rα mediated signaling has been established during acute schistosomiasis, where IL-4Rα deficient mice but not wild-type (wt) mice died around 6 to 8 weeks after natural infection with S. mansoni." (PMID 28827803, 2017). "However, there are few studies reporting the role of IL-4Rα in human monocytes and the role of this molecule in schistosomiasis remains controversial." (PMID 24757288, 2014). "Moreover, B cell responses were significantly abrogated in mice lacking IL‐4Rα expression on CD11c+ cells compared to control mice, suggesting that IL‐4Rα‐expressing CD11c+ cells play an important role in the development of adaptive immune responses during schistosomiasis." (PMID 30500088, 2019). "Using transgenic mice that lacked IL-4Rα expression on B cells (mb1creIL-4Rα−/lox), we showed that mice lacking this subset of B cells are susceptible to schistosomiasis, succumbing to disease earlier than both littermate controls and global B cell deficient mice." (PMID 30619289, 2018). "Hence, it is possible that IL-4Rα up-regulation on Foxp3+ Treg cells during acute experimental schistosomiasis observed in our study could occur as an attempt for the host to rapidly mount a protective Th2 immune response during acute schistosomiasis." (PMID 30379806, 2018). "Interestingly, we found that B cell-specific IL-4Rα-deficient mice were highly susceptible to schistosomiasis suggesting that the lack of IL-4Rα expression on B cells, similarly to complete B-cell depletion sufficiently prevents the development of host protective immunity during schistosomiasis." (PMID 30619289, 2018). "This indicated that IL-4Rα is necessary for host survival during acute schistosomiasis, but not required for host survival at the chronic phase of the disease." (PMID 28827803, 2017). "Although the absence of IL-4Rα-dependent aaMφ and T cell responses during schistosomiasis has been mainly studied at the systemic level, little is known of their specific role(s) in the liver granuloma microenvironment." (PMID 20502521, 2010).
colitis (9 papers, 2015 to 2023). Inflammation of the colon. "In the present study, we investigated the role of IL-4Rα in intestinal mucosal inflammation using a model of dextran sulfate sodium (DSS)-induced colitis in IL-4Rα-deficient (IL-4Rα-/-) mice." (PMID 33192516, 2020). "To address the role that IL-4/IL-13 signalling plays on macrophages in oxazolone-induced colitis, we used the macrophage/neutrophil-specific IL-4Rα-deficient mouse strain (LysMcreIL-4Rα-/lox)." (PMID 32410852, 2020). "Oxazolone induced a rapid onset colitis marked by weight loss in both hemizygous littermate controls (IL-4Rα-/lox) and VillincreIL-4Rα-/lox mice." (PMID 32410852, 2020). "Our own studies have demonstrated that CD4+ T cells and B cells deficient in the IL-4/IL-13 common receptor IL-4Rα are protected from oxazolone-induced colitis." (PMID 32410852, 2020). "By deleting IL-4Rα on specific cell subsets shown to play a role in mediating colitis, we determined their role in a loss of function approach." (PMID 32410852, 2020). "Mice deficient in IL-4Rα exhibited obvious amelioration of symptoms of DSS-induced colitis such as diarrhea, rectal bleeding, colon shortening, and destruction of the colonic mucosal structure." (PMID 33192516, 2020). "Oxazolone induced a rapid onset colitis marked by weight loss and mortality in both hemizygous littermate controls (IL-4Rα-/lox) and LysMcreIL-4Rα-/lox mice." (PMID 32410852, 2020). "Wild-type (WT), Stat6 knockout (Stat6−/−), and intestinal epithelial cell-specific IL-4Rα knockout (Il-4rαΔIEC) mice were subjected to colitis-associated (AOM/DSS) and colitis-independent (sporadic) carcinogenesis." (PMID 30353167, 2019). "Apart from decreasing apoptosis in cell lines such as HCT116, IL4Rα contributed to tumor formation in a mouse model of colitis-associated cancer and mediated proliferation of epithelial tumor cells." (PMID 30326660, 2018). "Hence, the smooth muscle cell-specific IL-4Rα-deficient mouse strain provided us with a tool to understand the role of IL-4/IL-13-reponsive smooth muscle cells in oxazolone colitis." (PMID 32410852, 2020). "Therefore, the epithelial cell-specific IL-4Rα-deficient mouse strain would be able to directly test the effect of IL-13 signalling on epithelial cells and disease onset in oxazolone colitis." (PMID 32410852, 2020). "Therefore, it is possible that IL4Rα expression in other cell types, such as colonic epithelial cells, could have an important role in promoting the development of colitis-associated colon tumorigenesis." (PMID 34681866, 2021). "Increased sensitivity to DSS-induced colitis was caused by elevated cell death in response to the initial carcinogen exposure as Stat6 deficiency led to increased chromatin compaction affecting DNA damage response in IEC upon treatment with alkylating agents independently of IL-4Rα engagement." (PMID 30353167, 2019). "The differential expression analysis using TAC showed that the expression level of 91 genes was altered by DSS treatment and 47 genes were differentially expressed between IL-4Rα-/- colitis and WT colitis mice." (PMID 33192516, 2020). "Neutrophil infiltration in the colonic mucosa was reduced in IL-4Rα-/- colitis mice compared with WT colitis mice." (PMID 33192516, 2020). "In the present study, the infiltration of neutrophils and the upregulation of CXCL2 and IL-1β observed in colonic tissues of colitis mice were significantly suppressed in the IL-4Rα-/- mice." (PMID 33192516, 2020). "Macroscopic observations of colons on day 7 showed that colon shortening occurred in WT colitis mice but was significantly alleviated in IL-4Rα-/- colitis mice (7.5 ± 0.2 cm in WT colitis, 10.1 ± 0.5 cm in IL-4Rα-/- colitis; p < 0.001)." (PMID 33192516, 2020). "Our results indicate that the development of DSS-induced colitis is alleviated in IL-4Rα-/- mice through enhancement of NOX1-derived ROS production in the colon." (PMID 33192516, 2020).
colitis (continued). "To investigate changes in colonic gene expression levels between WT colitis and IL-4Rα-/- colitis mice, we performed transcriptome analysis on colonic tissues obtained on day 7 after initiation of DSS treatment." (PMID 33192516, 2020). "The elevated FITC-dextran level was markedly decreased in the IL-4Rα-/- colitis mice (673.9 ± 42.1 pg/ml in WT colitis, 204.0 ± 41.5 pg/ml in IL-4Rα-/- colitis; p < 0.001)." (PMID 33192516, 2020). "The mRNA expression of Il-4 was significantly lower in IL-4Rα-/- colitis mice than in WT colitis mice." (PMID 33192516, 2020). "While it still remains to be determined if IL-4Rα expression on macrophages plays a role in chronic oxazolone colitis, we conclude that IL-4Rα expression on macrophages and neutrophils plays a redundant role in acute oxazolone colitis." (PMID 32410852, 2020). "Among 47 genes, 10 genes were upregulated and 37 genes were downregulated in IL-4Rα-/- colitis mice compared with WT colitis mice." (PMID 33192516, 2020). "The number of infiltrated neutrophils in the colonic mucosa of IL-4Rα-/- colitis mice was dramatically reduced compared to that in WT colitis mice (169.9 ± 24.5 in WT colitis, 78.9 ± 11.7 in IL-4Rα-/- colitis; p < 0.001)." (PMID 33192516, 2020). "Given the findings of our present study, we conclude that IL-4Rα deficiency enhances NOX1-dependent ROS production and intestinal mucosal barrier function, resulting in the suppression of colitis development." (PMID 33192516, 2020). "These histological abnormalities were significantly ameliorated in the colons of IL-4Rα-/- colitis mice (5.5 ± 0.3 in WT colitis, 2.5 ± 0.2 in IL-4Rα-/- colitis; p < 0.001)." (PMID 33192516, 2020). "In an attempt to identify the responsible IL-4Rα-expressing cell type, we expanded our studies to include other cells known to be involved in colitis, including intestinal epithelial cells, smooth muscle cells, and macrophages." (PMID 32410852, 2020). "On day 4 after DSS treatment via the drinking water, a decrease in body weight was observed in WT colitis mice but was significantly suppressed in IL-4Rα-/- mice." (PMID 33192516, 2020). "Treatment with DSS caused body weight loss, an increase in the disease activity index and histological abnormalities in WT colitis mice, all of which were significantly attenuated in IL-4Rα-/- colitis mice." (PMID 33192516, 2020). "This suggests that a regulatory role of IL-4Rα is required to protect against severe colitis." (PMID 32410852, 2020). "Furthermore, elevated intestinal permeability induced by DSS treatment was suppressed in IL-4Rα-/- colitis mice." (PMID 33192516, 2020). "However, the cell populations responsible for regulating the severity of disease onset through IL-4Rα in colitis are yet to be identified." (PMID 32410852, 2020). "(78.5 ± 2.0% in WT colitis, 92.6 ± 1.4% in IL-4Rα-/- colitis mice on day 7; p < 0.001)." (PMID 33192516, 2020). "Together, our data provides evidence that IL-4Rα signalling on intestinal epithelial cells, smooth muscle cells, macrophages, and neutrophils is not essential in mediating or reducing the inflammatory responses that drive pathology in a mouse model of colitis." (PMID 32410852, 2020). "However, we found only a very minor reduction in disease pathology and therefore concluded that IL-4Rα-expressing smooth muscle cells play a redundant role in oxazolone colitis." (PMID 32410852, 2020). "Therefore, the IL-4Rα-expressing cell type responsible for the regulation of IL-4/IL-13 signalling during oxazolone colitis remains to be determined." (PMID 32410852, 2020). "Furthermore, the top 10 upregulated and downregulated genes in IL-4Rα-/- colitis mice compared to WT colitis mice were shown in the heat map." (PMID 33192516, 2020).